IGF1R (insulin like growth factor 1 receptor)
Diseases named in the same sentence as IGF1R in open-access papers (continued):
Sharing a sentence is not in itself a finding about the gene and the disease.
melanoma (continued). "Bioinformatic analysis using several web-based tools showed that miRNA-376a and miRNA-376c have putative binding sites at the 3'UTR of IGF1R, a tyrosine kinase receptor long known to be implicated in melanoma tumorigenesis and progression." (PMID 22747855, 2012). "More specifically, the possibility of targeting the IGF1R by siRNAs in B-RAF-mutated melanoma cells was also already suggested several years ago." (PMID 22747855, 2012). "Rescue experiments revealed that the functions caused by LINC01291 downregulation in melanoma cells could be reversed by suppressing miR-625-5p or overexpressing IGF-1R." (PMID 33674778, 2022). "Our study identified the LINC01291/miR-625-5p/IGF-1R competing endogenous RNA pathway in melanoma cells, which may represent a novel diagnostic biomarker and an effective therapeutic target for melanoma." (PMID 33674778, 2022). "A recent study identified that a single nucleotide polymorphism (SNP) of IGF1R may have a protective effect for melanoma risk in support that differential IGF1R signaling is involved in melanoma development." (PMID 34831014, 2021). "Here we studied the melanoma associations of selected SNPs from the ER/IGF1R network." (PMID 32150843, 2020). "In summary, our data might suggest that the G allele in IGF1 rs1520220 is likely to be associated with melanoma risk, while the A allele in IGF1R rs2229765 may have a protective effect, especially in men, in recessive genetic models." (PMID 32150843, 2020). "While this silent mutation of rs2229765 polymorphism favored longevity in male carriers of the homozygous A alleles, the protective effect of IGF1R rs2229765 in the current study in men remains an interesting focal point in future melanoma gender disparity studies." (PMID 32150843, 2020). "Finally, the laboratory of Valentine Macaulay has shown that downregulation of IGF1R in melanoma cells was associated with enhanced radiosensitivity." (PMID 27446805, 2016). "LINC01291 was found to increase the expression level of IGF-1R (insulin-like growth factor-1 receptor) by competing with miR-625-5p, which exhibits pro-oncogenic roles in melanoma." (PMID 40622919, 2025). "For example, the inhibition of IGF1R function was found to promote melanoma cell apoptosis, whereas deletion of Syntenin-1 in a melanoma mouse model resulted in delayed tumor onset and reduced occurrence of distant metastases." (PMID 41155412, 2025). "Performing IGF‐1R chromatin immunoprecipitation‐sequencing (ChIP‐seq) in cultured human melanoma cells, Larsson and colleagues identified 568 mostly intergenic IGF‐1R binding regions, with several shown to mediate transcriptional activation." (PMID 41028981, 2025). "LINC01291 promotes melanoma aggressiveness by acting as a ceRNA that sponges miR-625-5p to sustain the expression of insulin-like growth factor 1 receptor (IGF-1R)." (PMID 39068483, 2024). "The insulin-like growth factor 1 receptor (IGF1R)/PI3K pathway was activated as an acquired resistance mechanism to the BRAFi SB-590885 in BRAFV600E melanoma cells." (PMID 37834284, 2023). "Further, our results demonstrated that LINC01291 promotes the oncogenicity of melanoma cells by serving as a molecular sponge for miR-625-5p, thereby reinforcing IGF-1R expression." (PMID 33674778, 2022). "After experimental pulmonary metastasis, IGF1R-deficient mice exhibited reduced tumor implantation in both LLC and melanoma models, as similarly observed upon heterotopic syngeneic transplantation." (PMID 35688943, 2022). "In summary, our study confirmed the involvement of LINC01291, miR-625-5p, and IGF-1R in melanoma and identified the LINC01291/miR-625-5p/IGF-1R ceRNA pathway." (PMID 33674778, 2022). "MicroRNA-139-5p modulates the growth and metastasis of malignant melanoma cells via the PI3K/AKT signaling pathway by binding to IGF1R (binding energy -8.6 kcal/mol)." (PMID 36686654, 2022).
melanoma (continued). "Then, the regulatory effects of miR-625-5p on IGF-1R expression in melanoma cells were determined via qRT-PCR and western blotting." (PMID 33674778, 2022). "BRAFi resistant melanoma cells upregulate several RTKs, but only co-targeting IGF1R and MEK exacerbates cell death." (PMID 35966590, 2022). "Arbiser and collaborators, while aiming to develop chemotherapeutic NPs to target receptors overexpressed in most advanced melanomas (IGF1R and CD44), prepared hyaluronic acid (HA) NPs for physical encapsulation of an active organopalladium compound (Pd1)." (PMID 35890401, 2022). "Correlation analysis further revealed a positive correlation between LINC01291 and IGF-1R expression in melanoma tissues (r = 0.6193, P < 0.0001)." (PMID 33674778, 2022). "Apart from handling the transcription, IGF1R can trigger the growth and metastasis of malignant melanoma cells through the PI3K-Akt signaling pathway." (PMID 36686654, 2022). "In general, these results suggest that LINC01291 exhibits pro-oncogenic roles in melanoma cells by targeting the miR-625-5p/IGF-1R axis." (PMID 33674778, 2022). "We performed immunofluorescence in tissue sections of 20 human melanoma biopsies with markers of active IGF1 signaling (phospho-IGF1R) and adherens junctions (α-catenin) and independently evaluated NECTIN1 expression." (PMID 36229674, 2022). "Mechanistically, LINC01291 functions as a competing endogenous RNA by sponging microRNA-625-5p (miR-625-5p) in melanoma cells and maintaining insulin-like growth factor 1 receptor (IGF-1R) expression." (PMID 33674778, 2022). "It has been indicated that the IGF-1R expression in melanomas is regulated by the surrounding stromal cells as well as the PTEN and BRAF status." (PMID 34830178, 2021). "This research opens up avenues for the development of novel and potent IGF1R/IR inhibitors for patients with BRAF-mutant melanoma." (PMID 34831014, 2021). "Specifically, genes upregulated or downregulated in response to UV radiation involve CDKN1C, CDK2, COL11A1, KIT, and IGF1R, the majority of which are identified as differentially upregulated in melanoma versus atypical tumor or nevus." (PMID 35052351, 2021). "E2F1, a transcription factor with diverse roles in apoptosis and the cell cycle, is upregulated in BRAFi-resistant melanoma and increases the expression of insulin-like growth factor 1 receptor (IGF-1R)." (PMID 33807778, 2021). "Other studies have shown that simultaneous inhibition of the MAPK, PI3Kβ/IGF1R, and PI3Kα pathways induced apoptosis and inhibited tumor growth in BRAF-mutant and loss-of-function PTEN melanoma models." (PMID 33807778, 2021). "It has been reported that integrin subunit beta 3 (ITGB3) is positively related to a higher frequency of malignant melanomas than benign lesions, and insulin-like growth factor 1 receptor was found to be involved in adaptive bypass of BRAFV600E inhibition." (PMID 34106558, 2021). "When IGF1R is suppressed by siRNA, mouse melanoma cells fail to induce ATM kinase activity after irradiation, suggesting that IGF1R plays a critical role in mediating ATM." (PMID 34178997, 2021). "It is reasonable to consider IGF-1R a good target in canine melanoma, based on its high expression and the so far encouraging results in human melanoma." (PMID 33664868, 2021). "Estrogen receptors (ERs) and insulin-like growth factor 1 receptor (IGF1R) show extensive crosstalk in cancer development, but how the ER/IGF1R network impacts melanoma is currently unclear." (PMID 32150843, 2020). "A recent work on melanoma shows the presence of one SNP in IGF1 and another in IGF1R, likely associated with increased risk or protective effect, respectively, especially in men." (PMID 32645881, 2020).
melanoma (continued). "To assess effects of IGF-1 responsivity in determining patient survival, we conducted a similar comparison between melanoma patients within the top and bottom quartiles for IGF-1R expression levels and obtained similar results." (PMID 33291663, 2020). "Using realtime RT-qPCR, immunocytochemistry and western blotting, we evaluated RNA and protein expression levels of GH and GHR, as well as IGF-1 and IGF-1R in human and mouse melanoma cell lines." (PMID 33291663, 2020). "Overexpression of the IGFBP5 mediator of insulin-like growth factor receptor (IGF1R) signalling inhibits the transformation of human melanoma cells in culture whilst TNS1 expression is down-regulated in multiple cancers including melanoma." (PMID 31881017, 2019). "IGF1R has been found to be upregulated in melanoma cells and is thought to be involved in numerous pathways that regulate cell survival and proliferation." (PMID 30824801, 2019). "The rationale for combining these drugs is that several proteins, which are linked to melanoma cell response and resistance to BRAFV600/MEK-targeting agents, are HSP90 clients including ARAF, CRAF, BRAFV600E, CDK4, COT, IGF1R, PDGFR-β and AKT." (PMID 30989459, 2019). "Altogether, these data suggest that GCNT2/I-branched glycans regulate IGF1R and integrin growth and survival pathways in melanoma cells." (PMID 30135430, 2018). "Expression-based analyses using publicly available databases revealed that melanomas have high expression of IGF1R, as well as high expression of several different integrin α and β chains." (PMID 30135430, 2018). "Together, these data suggest that GCNT2/I-branch expression modulates IGF-1 and RGD binding activity on melanoma cells to potentially regulate IGF1R- and integrin-related signaling." (PMID 30135430, 2018). "IGF-1R is responsible for the transformation, proliferation, and metastasis of melanoma and maintains the malignant phenotype." (PMID 29946532, 2018). "To dissect how differential GCNT2/I-branched glycan expression modulates IGF1R and integrin activities in melanoma cells, we analyzed related signaling events." (PMID 30135430, 2018). "Among MAPK activators, IGF-1R is considered one of the most attractive targets for melanoma therapy." (PMID 29946532, 2018). "While we have demonstrated that I-branched glycans negatively regulate IGF1R- and integrin-mediated cell growth and survival signaling pathways in melanoma, the opposite outcome is also possible for the function of other glycoproteins." (PMID 30135430, 2018). "Then, after IGF1R was knockdown in the M8 and SK-Mel-19 cells using the appropriate siRNAs, the sensitivities of both cell lines to cisplatin were reduced.This suggested the direct correlationship between IGF1R and cisplatin-resistance in melanoma cells." (PMID 29642855, 2018). "Collectively, these data indicate that the modification of complex N-glycans with I-branched or i-linear glycan moieties elicits differential IGF1R and integrin signaling in melanoma cells." (PMID 30135430, 2018). "Additional studies focusing on a subset of potential N-glycan protein targets demonstrated that low GCNT2/I-branched glycan expression increased melanoma cell proliferation and survival by enhancing IGF1R- and integrin:ECM-mediated signaling." (PMID 30135430, 2018). "Treatment of GCNT2 KD, GCNT2 OE and control melanoma cell variants with IGF-1, the cognate ligand for IGF1R, revealed that low GCNT2/I-branched glycan levels increased melanoma cell proliferation." (PMID 30135430, 2018). "Through integrated transcriptomic, proteomic, and epigenomic analyses, we discover that SIRT6 haploinsufficiency increases IGFBP2 expression and promotes melanoma cell survival through the activation of IGF-1R/AKT signaling." (PMID 30143629, 2018).
melanoma (continued). "The activity of PI3K-AKT-mTOR pathway was also shown to be upregulated as a result of the overexpression or hyperactivation of RTKs such as c-Met, EGFR and IGF1R in melanoma cells." (PMID 28708099, 2017). "Here, we also observed that cell lines, both BRAF- and PTEN-mutated, were the most sensitive towards WP760, however further studies are required to prove that inhibition of IGF1R indeed contributes to WP760 anti-melanoma activity." (PMID 28417283, 2017). "We demonstrated that IGF-1 limits the effects of MEK1/2 inhibition in melanoma cells, while siRNA, by preventing IGF-1R de novo synthesis with a proportional, balanced overall decrease of its signaling, greatly increases the efficacy of MAPK targeting." (PMID 29137261, 2017). "Due to its ability to compensate for signals lost following therapeutic MAPK-inhibition, insulin-like growth factor type 1 receptor (IGF-1R) co-targeting is a rational approach for melanoma treatment." (PMID 29137261, 2017). "Having shown that IGF-1R signalling limits the effects of MEK1/2 inhibition in melanoma cells, we next evaluated different approaches to prevent IGF-1R activation." (PMID 29137261, 2017). "In our analysis, we found significant suppression of IGF2R on all melanoma cells following GHRKD but a significant rise in IGF1R and IR RNA levels following GHRKD especially when treated with excess GH." (PMID 28223541, 2017). "Since PCR array results suggested that IGF1R was involved in melanoma cells’ response to WP760, expression of this protein was evaluated." (PMID 28417283, 2017). "Western blot showed that addition of 100μM palmitate partially rescued C75 (50 μM) or IT (40 μM)-induced IGF-1R decreases in A375S and A2058 melanoma cells, respectively." (PMID 27323414, 2016). "Overexpression of IGF-1R partially reversed IT-induced cell growth inhibition, which suggested that IGF-1R signaling was involved in the anti-melanoma activities of IT." (PMID 27323414, 2016). "If such a system exists, the regulation of IGF-1R by RUNX2 shown in the present study would suggest the existence of a positive feedback loop of RUNX2/IGF-1/IGF-1R in melanoma cells, promoting melanoma migration and invasion." (PMID 27102439, 2016). "We next confirmed that the over-expressions of EGFR, IGF-1R and CRAF were closely associated with resistance to BRAFi in VemR A375 melanoma cells." (PMID 27448964, 2016). "We have demonstrated that RUNX2-deficient melanoma cells display a significant decrease in three receptor tyrosine kinases, EGFR, IGF-1R and PDGFRβ." (PMID 27102439, 2016). "IT pretreatment for 6 h did not reduce the levels of phosphorylatedIGF-1R in the IGF-1-stimulated melanoma cells, while IT pretreatment for 24 h significantly decreased the phosphorylated IGF-1R in the IGF-1-stimulated melanoma cells." (PMID 27323414, 2016). "Consistent with this, co-inhibition of MEK1/2 and IGF-1R or PI3K was more effective in inducing cell death in B-Raf inhibitor-resistant melanoma cells than when either inhibitor was used alone." (PMID 27342992, 2016). "Up-regulation of the expression of EGF-R, PDGFRβ, AXL and IGF-1R in melanoma cells that have developed resistance to BRAF V600E targeted therapy results in reactivation of the MAPK and the PI3K/AKT pathways." (PMID 27102439, 2016). "This conclusion is based on: 1) the down regulation of AXL, EGFR, IGF-1R and PDGFRβ in ShRUNX2 knocked down melanoma cell lines or RUNX2-specific U1 Adaptors-transfected melanoma cells." (PMID 27102439, 2016). "In this study, we evaluated the anti-melanoma activities of IT, and determined the cytotoxic mechanism through IGF-1R/STAT3 pathway." (PMID 27323414, 2016). "The contribution of IGF-1 to melanoma cell migration was shown to require the activation of PI3K by IGF-1R." (PMID 27102439, 2016).
melanoma (continued). "In a human melanoma cell line panel we assessed levels and activation of IGF-1R and its effectors AKT and ERKs, and expression of O6-methylguanine-DNA methyltransferase (MGMT) that removes the most toxic TMZ-induced DNA adduct, O6-methyguanine (O6-meG; )." (PMID 26497996, 2015). "Our results indicate a correlation between intrinsic TMZ resistance and IGF-1R activation, and show that two different small molecule IGF-1R inhibitors sensitize human melanoma cells to TMZ." (PMID 26497996, 2015). "Type 1 insulin-like growth factor receptor (IGF-1R) is frequently up-regulated in cancers including melanoma, and promotes proliferation and cell survival." (PMID 26497996, 2015). "While sites of phosphorylation of the insulin receptor substrate IRS-2 and IGFR2 indicated novel points of regulation in the IGF-1R pathway previously identified to mediate drug resistance in melanoma." (PMID 26029660, 2015). "The effect size was similar with both inhibitors, and comparable to TMZ-sensitization we previously reported in IGF-1R-depleted melanoma cells, supporting the contention that sensitization was related to IGF-1R inhibition." (PMID 26497996, 2015). "The important role of ErbB family and IGF-1R in melanoma growth and resistance to targeted therapy has been reported." (PMID 24920406, 2014). "In these analyses, we were able to confirm expression of transcripts specific for CD63, ErbB3, CD44, and IGF-1-R in melanoma cells and melanoma cell lines in all samples tested." (PMID 24489649, 2014). "IGF-1R/PI3K signaling was enhanced in resistant melanomas; combined treatment with IGF-1R/PI3K and MEK inhibitors induced death of BRAF inhibitor-resistant cells." (PMID 24743024, 2014). "The IGF-1-R was expressed on melanoma cells in 6 of 15 patient-derived melanoma samples tested, namely in 3 samples of freshly isolated cells and in 3 xenograft-samples." (PMID 24489649, 2014). "Insulin receptor substrates 1 and 2 (IRS1/2) mediate oncogenic signaling from IGF-1R and are upregulated in melanoma cell lines resistant to BRAF inhibitors or derived from patients that developed resistance to vemurafenib treatment." (PMID 24743024, 2014). "The results of our study show that melanoma cells display a unique composition of cell surface antigens, including ErbB3, IGF-1-R, CD44 and ICAM-1." (PMID 24489649, 2014). "We investigated the effect of ganetespib on signaling molecules that have been reported to be the clients of HSP90, including c-Met, EGFR, and IGF-1R, in a panel of five melanoma cell lines." (PMID 23418523, 2013). "As expected, both mRNA and protein levels of IGF1R were higher in melanoma cell lines than in normal melanocytes." (PMID 22747855, 2012). "In our experimental system, IGF1R levels were higher in melanoma cell lines than in normal melanocytes, and the ectopic expression of mir-376a and mir-376c led to down-regulation of the receptor." (PMID 22747855, 2012). "Insulin-like growth factor 1 (IGF-1) was shown by others to significantly increase melanoma cell migration in-vitro through activation of the IGF1R." (PMID 22747855, 2012). "Eight years ago the IGF1/IGF1R pair was shown to lead to melanoma migration, and in fact IGF1R was recently identified as a potential target in melanoma using a phosphoproteomic screen." (PMID 22747855, 2012). "The work presented here demonstrates that mir-376a and mir-376c negatively regulate IGF1R, and suggests that aberrations in this regulatory mechanism, in the form of down-regulation of mir-376a/c, take part in melanoma progression and metastasis." (PMID 22747855, 2012). "IGF1R has been shown to play a role in a number of malignancies including melanoma, breast, prostate, and lung." (PMID 19025658, 2008). "The insulin-like growth factor (IGF) axis is one such system which contributes to human malignancy, with overexpression of IGF1 receptor (IGF1R) noted in several cancers, including melanoma." (PMID 19025658, 2008).